TEK (TEK receptor tyrosine kinase)
Description:
Tyrosine-protein kinase that acts as a cell-surface receptor for ANGPT1, ANGPT2 and ANGPT4 and regulates angiogenesis, endothelial cell survival, proliferation, migration, adhesion and cell spreading, reorganization of the actin cytoskeleton, but also maintenance of vascular quiescence. Has anti-inflammatory effects by preventing the leakage of pro-inflammatory plasma proteins and leukocytes from blood vessels. Required for normal angiogenesis and heart development during embryogenesis. Required for post-natal hematopoiesis. After birth, activates or inhibits angiogenesis, depending on the context. Inhibits angiogenesis and promotes vascular stability in quiescent vessels, where endothelial cells have tight contacts. In quiescent vessels, ANGPT1 oligomers recruit TEK to cell-cell contacts, forming complexes with TEK molecules from adjoining cells, and this leads to preferential activation of phosphatidylinositol 3-kinase and the AKT1 signaling cascades. In migrating endothelial cells that lack cell-cell adhesions, ANGT1 recruits TEK to contacts with the extracellular matrix, leading to the formation of focal adhesion complexes, activation of PTK2/FAK and of the downstream kinases MAPK1/ERK2 and MAPK3/ERK1, and ultimately to the stimulation of sprouting angiogenesis. ANGPT1 signaling triggers receptor dimerization and autophosphorylation at specific tyrosine residues that then serve as binding sites for scaffold proteins and effectors. Signaling is modulated by ANGPT2 that has lower affinity for TEK, can promote TEK autophosphorylation in the absence of ANGPT1, but inhibits ANGPT1-mediated signaling by competing for the same binding site. Signaling is also modulated by formation of heterodimers with TIE1, and by proteolytic processing that gives rise to a soluble TEK extracellular domain. The soluble extracellular domain modulates signaling by functioning as decoy receptor for angiopoietins. TEK phosphorylates DOK2, GRB7, GRB14, PIK3R1; SHC1 and TIE1.
Synonyms: CD202b; TIE2; VMCM; VMCM1; TIE-2; GLC3E
Tractability: Small molecule: an approved drug acts on it; a structure with a bound ligand is known; a high-quality ligand is known; it has a high-quality binding pocket; it belongs to a druggable protein family. Antibody: UniProt places it where antibodies can reach, with high confidence; its Gene Ontology location is reachable by antibodies, with high confidence; UniProt predicts a signal peptide or a membrane-spanning region; the Human Protein Atlas places it where antibodies can reach. PROTAC: UniProt records ubiquitination sites on it; a small molecule that binds it is known.
Target class: TK protein kinase group; Enzyme; Tyrosine protein kinase Tie family; Protein Kinase; Kinase
Chemical probes: BAY-826 (high quality), CHEMBL373882 (high quality)
Gene: Protein-coding gene on chromosome 9 (27,109,030 to 27,232,092, forward strand). Ensembl gene ENSG00000120156.
Subcellular location: Cell membrane; Cell junction; Cell junction, focal adhesion; Cytoplasm, cytoskeleton; Secreted
Subcellular location (Human Protein Atlas): Plasma membrane; Basal body; Centrosome; Predicted to be secreted
Pathways (Reactome):
Hemostasis: Tie2 Signaling
Signal Transduction: RAF/MAP kinase cascade
Gene Ontology:
Molecular function: identical protein binding; protein binding; protein tyrosine kinase activity; transmembrane receptor protein kinase activity; transmembrane receptor protein tyrosine kinase activity; protein kinase activity; signaling receptor activity; ATP binding
Biological process: angiogenesis; cell surface receptor protein tyrosine kinase signaling pathway; cell surface receptor signaling pathway; cellular response to mechanical stimulus; negative regulation of angiogenesis; positive regulation of angiogenesis; positive regulation of endothelial cell migration; positive regulation of ERK1 and ERK2 cascade; positive regulation of focal adhesion assembly; positive regulation of intracellular signal transduction; positive regulation of MAPK cascade; positive regulation of phosphatidylinositol 3-kinase/protein kinase B signal transduction; positive regulation of Rac protein signal transduction; positive regulation of Rho protein signal transduction; regulation of establishment or maintenance of cell polarity; sprouting angiogenesis; substrate adhesion-dependent cell spreading; Tie signaling pathway; cell-cell signaling; definitive hemopoiesis; endothelial cell proliferation; glomerulus vasculature development; heart development; heart trabecula formation; negative regulation of apoptotic process; and 14 more
Cellular component: actin filament; anchoring junction; apical plasma membrane; basal plasma membrane; basolateral plasma membrane; cell surface; cell-cell junction; extracellular region; membrane raft; microvillus; plasma membrane; stress fiber; receptor complex; cytoskeleton; focal adhesion
Genetic constraint (gnomAD): Loss-of-function variants: 36 observed, 129.05 expected, observed/expected ratio (o/e) 0.28, 90% interval 0.21 to 0.37. The upper end of that interval is the gene's LOEUF score, 0.37, which puts it in group 1 of 6, group 1 being the genes least tolerant of losing a copy. Missense variants: 1,141 observed, 1,441.8 expected, observed/expected ratio (o/e) 0.79, 90% interval 0.75 to 0.83. Synonymous variants: 578 observed, 516.62 expected, observed/expected ratio (o/e) 1.12, 90% interval 1.04 to 1.2.
Homologues: Orthologues: chimpanzee TEK (99% identical), macaque TEK (98% identical), dog TEK (95% identical), pig TEK (93% identical), rat Tek (93% identical), mouse Tek (93% identical), rabbit TEK (88% identical), guinea pig TEK (84% identical), tropical clawed frog tek (67% identical), zebrafish tek (52% identical). Paralogues in human: TIE1 (47% identical), EPHA2 (18% identical), EPHA3 (18% identical), EPHA5 (18% identical), EPHA6 (18% identical), EPHB3 (18% identical), EPHA7 (18% identical), EPHB1 (17% identical), EPHA4 (17% identical), FGFR2 (17% identical), FGFR1 (17% identical), EPHB4 (17% identical), and 41 more.
Diseases named in the same sentence as TEK in open-access papers:
TEK is named in the same sentence as 351 diseases in open-access papers, as found by Europe PMC text mining. Sharing a sentence is not in itself a finding about the gene and the disease. The quoted sentences say what the papers report.
breast cancer (58 papers, 2000 to 2025). A primary or metastatic malignant neoplasm involving the breast. "NG2 ablation also diminishes the number of tumor-associated and TEK tyrosine kinase endothelial (Tie2) expressing macrophages in mammary tumors, providing another possible mechanism for reducing tumor vascularization and growth." (PMID 22531600, 2012). "SIRT7 also counteracts metastasis in doxorubicin-resistant breast cancer cells by epigenetically repressing the tyrosine kinase receptor TIE2/TEK via H3K18 deacetylation at its gene promoters, which would otherwise promote migration." (PMID 41471349, 2025). "Besides, changes in TEK expression have been observed in tumor tissues including breast cancer, gastric cancer, thyroid cancer, and ccRCC." (PMID 40028163, 2025).
Venous malformation (47 papers, 2011 to 2026). A vascular malformation resulting from a developmental error of venous tissue composed of dysmorphic channels lined by flattened endothelium and exhibiting slow turnover. "Further studies revealed somatic GoF TEK variants (mainly L914F) in ~50% sporadic venous malformations, and in PIK3CA (mainly hotspot variants E542K, E545K, and H1047R) in 20%." (PMID 41272322, 2026). "In 1996, germline GoF TEK variants were identified as the cause of cutaneous-mucosal venous malformations, a rare autosomal dominant VM syndrome." (PMID 41272322, 2026). "TEK mutations (including L914F) have been shown to induce venous malformations in more than 75% of zebrafish embryos, which closely recapitulate the clinical features observed in human patients." (PMID 41153341, 2025). "Gain-of-function mutations in TIE2 (gene TEK) underlie inherited venous malformations (VMCM), whereas TIE2 loss-of-function mutations cause primary congenital glaucoma (PCG)." (PMID 38820174, 2024). "Mutations in TIE2/TEK (PI3K/AKT/mTOR pathway) have been identified in venous malformations and blue rubber bleb nevus syndrome." (PMID 38790562, 2024). "Sporadic venous malformations are genetic conditions primarily caused by somatic gain-of-function mutation of PIK3CA or TEK, an endothelial transmembrane receptor signaling through PIK3CA." (PMID 38880808, 2024). "The hotspot GNAQ p.R183Q and TEK p.L914F mutations were responsible for the majority of port-wine stain/Sturge–Weber syndrome and venous malformation, respectively." (PMID 37658401, 2023). "It has a high mutational component, with overexpression of genes associated with angiogenesis, such as TIE1, VEGFR2, SNF-1, TEK (kinase associated with venous malformations), and FLT1." (PMID 36555675, 2022). "Nearly half of sporadic venous malformations (VMs) bear activating TEK mutations, while most others express activating PIK3CA H1047R, or E452K or C420R mutations, in a mutually exclusive manner." (PMID 36353506, 2022). "In the princeps study in 2009, it was demonstrated that somatic genetic mutations are associated with sporadically occurring vascular anomalies: isolated venous malformations (VM) were discovered to have somatic TIE2/TEK mutations." (PMID 34112235, 2021). "These include somatic mutations in RASA1 in lesions from patients with capillary malformation-arteriovenous malformation (CM-AVM) and TIE2 (TEK) somatic mutations in lesions from patients with venous malformations as predominant examples." (PMID 33167572, 2020). "Genetic abnormalities contribute only 2% of reported venous malformations; however, recent studies revealed mutations in the TEK gene, encoding Tie2, in the families with dominant inheritance of venous malformations." (PMID 22187650, 2012). "The TEK mutation in patient 13 can cause multiple sporadic venous malformations." (PMID 36175890, 2022). "TIE2/TEK gene mutations are thought to be causative in most isolated venous malformations." (PMID 33194911, 2020). "Mutations in TEK were previously associated with autosomal dominant forms of venous malformations." (PMID 24358131, 2013). "A somatic loss-of-function mutation in TEK causing local loss of the wild-type allele in combination with a weakly activating germline mutation in the same gene was discovered in a venous malformation from an individual with inherited mucocutaneous venous malformation." (PMID 40648852, 2025). "On the other hand, the TEK mutation may explain the onset of venous malformations." (PMID 33105631, 2020). "The first somatic variants associated with sporadic VMs were found in TEK (Tyrosine kinase with immunoglobulin and EGF homology domains), in patients with venous malformations." (PMID 41272322, 2026). "Genetic investigations have linked some venous malformations to specific mutations, notably in the TIE2 (TEK) gene." (PMID 40619100, 2025).
Venous malformation (continued). "Specifically, PIK3CA-related venous malformations showed a mean reduction of 33.4% (SD, ± 22.1) from the baseline at 6 months, while TEK-related venous malformations demonstrated a mean reduction of 27.8% (SD, ±18.9)." (PMID 38880808, 2024). "And recurrently mutated genes were identified in several vascular malformations as well including TEK/TIE2 mainly in venous malformations, GNA11/14 mainly in vascular tumors, KRAS/NRAS/RASA1/HRAS mainly in AVMs, GNAQ, IDH1/2, AKT1, PTEN and PIK3CA." (PMID 34736485, 2021). "Gain-of-function mutations of the RTK TIE2/TEK, which also leads to the activation of PI3K signaling, are responsible for around half of venous malformations in humans." (PMID 33078209, 2021). "Here, we again confirmed that most venous malformations are caused by somatic mutations in PIK3CA and TEK, although a genotype–phenotype correlation is difficult to establish, since patients with the same mutation can manifest different kinds of malformations." (PMID 33105631, 2020). "Somatic gain-of-function mutations in TEK and PIK3CA were discovered in venous malformations." (PMID 40648852, 2025). "It is essential to know that activating but not inactivating TEK variants can lead to multiple cutaneous and mucosal venous malformations (VMCM)." (PMID 39498435, 2024). "Sporadic venous malformations, the most common type of vascular malformations, are caused by gain‐of‐function mutations either in the endothelial tyrosine kinase receptor TEK/TIE2 or in the PI3K catalytic subunit alpha PIK3CA; with TEK and PIK3CA mutations largely being mutually exclusive." (PMID 35695059, 2022). "Importantly, about 30% of patients suffering from venous malformations without a TIE2/TEK mutation have been discovered to contain a gain-of-function mutation in the PI3KCA gene, showing the central role of this pathway in this type of vascular anomalies." (PMID 33078209, 2021). "We identified somatic variants within 26 of 44 (59%) individuals with slow-flow anomalies (either lymphatic malformation, venous malformation (VM), or mixed lymphatic/venous malformations) within the genes PIK3CA, TEK, GNAQ, BRAF, GNA11, and PIK3R1 with VAFs ranging between 0.7% to 24.8%." (PMID 39669602, 2024).
glioma (35 papers, 2010 to 2024). A benign or malignant brain and spinal cord tumor that arises from glial cells (astrocytes, oligodendrocytes, ependymal cells). "Knockdown of TEK increased the proliferation and migration of clear cell renal cell carcinoma; however, the overexpression of TEK in glioma cells was associated with tumor malignancy and drug resistance." (PMID 35550582, 2022). "Our group has previously reported that the tyrosine kinase receptor Tie2/TEK is expressed in glioma cells and brain tumor stem cells and is associated with the malignant progression of these tumors." (PMID 21321379, 2010). "In addition, TEK activation is associated with chemoresistance in glioma by increasing ATP-binding cassette (ABC) transporter expression." (PMID 32526933, 2020). "Analysis of the Chinese Glioma Genome Atlas Network (CGGA) dataset showed that higher SOCS3, VEGFA, and TEK expression levels are observed in GBM cases with wildtype (WT) IDHs." (PMID 33804433, 2021). "Five out of the ten top hub nodes from general glioma networks from StringDB and BioGRID are matching genes containing erb-b2 receptor tyrosine kinase 2 (HER2), erb-b2 receptor tyrosine kinase 4 (HER4), cyclin D3 (CCND3), TEK tyrosine kinase (TEK), and transforming growth factor alpha (TGFA)." (PMID 31952211, 2020).
Stroke (31 papers, 2009 to 2026). Sudden impairment of blood flow to a part of the brain due to occlusion or rupture of an artery to the brain. "SNPs in the ANXA2, TEK and TGFBR3 gene loci were associated with stroke risk, the TGF-β/BMP pathway is associated with several SCD subphenotypes, while polymorphisms within the UGT1A1 are associated with increased serum bilirubin levels and cholelithiasis." (PMID 34071035, 2021). "Five single nucleotide polymorphisms (SNPs) tested in children with SCD were significantly associated with stroke risk, namely ANXA2 (rs11853426), TEK (rs489347), and TGFBR3 (rs284875) variants, whereas ADCY9 (rs2238432) and ∝ -thalassemia were linked with decreased stroke risk." (PMID 35781614, 2023). "Although our review of the literature does not suggest that his infarct can be explained by the factor V Leiden heterozygosity, he was not tested for any of the other genetic variants that have been recently found to be associated with stroke in SCD such as ANXA2, TGFBR3, and TEK." (PMID 23972124, 2013). "Also, there have been a few single nucleotide polymorphisms (SNPs) in persons with SCD that have been found to be associated with increased stroke risk: ANXA2, TGFBR3, and TEK were noted in a study including these SNPs." (PMID 23972124, 2013).
glioblastoma (29 papers, 2012 to 2025). The most malignant astrocytic tumor (WHO grade IV). "Additionally, as a predictor of non-reactivity, elevations in SDF-1 alpha levels are found in patients with recurrent glioblastoma showing tumor progression, and elevations in TIE2 (TEK receptor tyrosine kinase 2) are also observed in association with tumor progression." (PMID 36732815, 2023).
diabetes (28 papers, 2011 to 2024). "Although the functional relevance of rs666478 associating with eGFR needs to be explored, genetic variants located about 5 Mb upstream of TEK on cyclin-dependent kinase inhibitor (CDKN) 2A, 2B genes have been previously associated with type 2 diabetes mellitus and coronary heart disease." (PMID 24358131, 2013).